DUXAP9 (double homeobox A pseudogene 9 )
Gene: Long non-coding RNA gene on chromosome 14 (19,062,294 to 19,131,345, forward strand). Ensembl gene ENSG00000293329.
Diseases named in the same sentence as DUXAP9 in open-access papers:
DUXAP9 is named in the same sentence as 13 diseases in open-access papers, as found by Europe PMC text mining. Sharing a sentence is not in itself a finding about the gene and the disease. The quoted sentences say what the papers report.
renal cell carcinoma (4 papers, 2019 to 2022). "The oncogenic potential of DUXAP9 has been explored in various cancers, including thyroid cancer, nonsmall cell lung cancer, bladder cancer, and renal cell carcinoma." (PMID 36614082, 2022). "Functional experiments showed that DUXAP8 and DUXAP9 enhanced but miR-29c-3p weakened growth of renal cell carcinoma." (PMID 31409759, 2019). "DUXAP9 has been explored as an oncogene promoting the tumor progression in bladder cancer, thyroid cancer, non‐small cell lung cancer as well as the growth of renal cell carcinoma." (PMID 34168980, 2021). "Our current results indicated that DUXAP8 and DUXAP9 may act as two key oncogenes in renal cell carcinoma through upregulation of COL1A1 and COL1A2 by competitively binding miR-29c-3p." (PMID 31409759, 2019). "Finally, we detected proliferative roles of DUXAP8, DUXAP9 and miR-29c-3p in renal cell carcinoma cell lines." (PMID 31409759, 2019). "Taken together, miR-29c-3p may be a potential binding miRNA of DUXAP8 and DUXAP9 in renal cell carcinoma." (PMID 31409759, 2019). "Moreover, functional experiments demonstrated that knockdown of pseudogenes DUXAP8/DUXAP9 reduced proliferative ability of renal cell carcinoma." (PMID 31409759, 2019). "These bioinformatic analytic findings indicate that pseudogene DUXAP8 and DUXAP9 may fuel onset and development of renal cell carcinoma by targeting COL1A1 and COL1A2 through competitively binding miR-29c-3p." (PMID 31409759, 2019). "Firstly, we determined the expression levels of five constituents (DUXAP8, DUXAP9, miR-29c-3p, COL1A1 and COL1A2) in 20 pairs of clinical cancer tissues and normal tissues of renal cell carcinoma." (PMID 31409759, 2019). "All these findings suggest that pseudogene DUXAP8/DUXAP9-miR-29c-3p-COL1A1/COL1A2 may be a critical signaling pathway in onset and progression of renal cell carcinoma." (PMID 31409759, 2019). "Taken together, amplification of pseudogenes DUXAP8 and DUXAP9 may lead to increase expression of COL1A1 and COL1A2 by competitively binding to miR-29c-3p, resulting in uncontrolled cell proliferation in renal cell carcinoma." (PMID 31409759, 2019).
renal carcinoma (3 papers, 2021 to 2023). A carcinoma arising from the epithelium of the renal parenchyma or the renal pelvis. "To clarify the molecular mechanism underlying the pro-tumor effects of DUXAP9 in renal cancer cells, we did a bioinformatics analysis." (PMID 34168980, 2021). "We further explored the effect of DUXAP9 on RCC in migration and invasion, as our results showed that high DUXAP9 expression was significantly associated with poor PFS in patients with renal cancer cells." (PMID 34168980, 2021). "Tan and his colleagues found that N6-methyladenosine modification of lncRNA DUXAP9 promoted renal cancer cell proliferation migration and invasion by boosting the PI3K/AKT signaling." (PMID 36825082, 2023). "The results of one of the studies indicate that DUXAP9 knockdown diminished the activation of Akt signalling in renal cancer cells." (PMID 36614082, 2022). "The regulation of Snail, a transcriptional repressor of epithelial genes by DUXAP9 was shown to promote EMT in renal cancer cells." (PMID 36614082, 2022). "In this study, using western blotting and in vitro (cell line) assays, we showed that DUXAP9 is an important regulator of Snail and promotes the invasion and migration in renal cancer cells." (PMID 34168980, 2021). "This study provides a more detailed understanding of DUXAP9 as a new potential target for the diagnosis and treatment of renal cancer." (PMID 34168980, 2021). "Meanwhile, we next evaluated that management of LY294002 in renal cancer cells also impaired the advancement of tumor cells growth of DUXAP9-overexpression cells through CCK-8 assays and colony formation assays." (PMID 34168980, 2021). "This is consistent with our findings that DUXAP9 knockdown reduced the activation of Akt signaling in renal cancer cells." (PMID 34168980, 2021). "A classical m6A motif (GAACT) was found in the DUXAP9 sequence using SRAMP (an m6A modification site predictor), so we wondered whether DUXAP9 exhibited m6A modification, which could maintain its fate in renal cancer cells." (PMID 34168980, 2021). "To further validate this hypothesis, we used LY294002 to inhibit PI3K, which abrogated the tumorigenic effects of DUXAP9 in renal cancer cells." (PMID 34168980, 2021). "DUXAP9 knockdown in renal cancer cells inhibited renal cancer cells proliferation and motility capacities in vitro and reversed epithelial–mesenchymal transition (EMT), whereas overexpression of DUXAP9 promoted renal cancer cells proliferation and motility capacities in vitro and induced EMT." (PMID 34168980, 2021). "The data confirmed that DUXAP9 is an important mediator in the Akt regulatory network, activating PI3K to induce Akt/mTOR signaling in renal cancer cells." (PMID 34168980, 2021). "Further, mechanistic studies showed that m6A modification of DUXAP9 allows it to exert its function by activating the PI3K/Akt signaling pathway and Snail expression in renal cancer cells." (PMID 34168980, 2021). "DUXAP9 promoted proliferation and motility capacities, suppressed apoptosis, and promoted EMT in renal cancer cells." (PMID 34168980, 2021). "DUXAP9 knockdown decreased Snail expression and inhibited EMT progression, while DUXAP9 overexpression activated Snail-induced EMT signaling in renal cancer cells." (PMID 34168980, 2021). "DUXAP9 activate PI3K/AKT pathway and Snail expression in renal cancer cells." (PMID 34168980, 2021). "Furthermore, we clarified that the stability of DUXAP9 was regulated by m6A modification, and DUXAP9 activated PI3K/Akt signaling pathway and Snail expression in renal cancer cells." (PMID 34168980, 2021).
non-small cell lung carcinoma (2 papers, 2019 to 2021). A group of at least three distinct histological types of lung cancer, including non-small cell squamous cell carcinoma, adenocarcinoma, and large cell carcinoma. "DUXAP9 has also been found to promote non-small-cell lung cancer progression by directly binding with Cbl-b and thus augmenting EGFR signaling." (PMID 31409759, 2019).
breast tumors (1 paper, 2022). "For example, events in CYB561 and CEACAM1 are enriched in HER2+, and E2F4, AP2A2, MGAT4B, and DUXAP9 events are enriched in basal-like breast tumors." (PMID 35044822, 2022).
head and neck squamous cell carcinoma (1 paper, 2023). A squamous cell carcinoma that arises from any of the following anatomic sites: lip and oral cavity, nasal cavity, paranasal sinuses, pharynx, larynx, and salivary glands. "Notably, DUXAP9 is upregulated in most cancers, including head and neck squamous cell carcinoma (HNSCC), in the TCGA database." (PMID 37401236, 2023).
kidney cancer (1 paper, 2019). Primary or metastatic malignant neoplasm involving the kidney. "Higher expression of DUXAP8 and DUXAP9 indicated poorer prognosis of kidney cancer." (PMID 31409759, 2019). "Moreover, our results suggested that DUXAP8 and DUXAP9 and other components in this pathway possessed significant prognostic values in patients with kidney cancer." (PMID 31409759, 2019).
lymph node metastasis (1 paper, 2023). "A high level of DUXAP9 is positively associated with lymph node metastasis, poor pathological differentiation, advanced clinical stage, worse overall survival, and worse disease‐specific survival in OSCC patients." (PMID 37401236, 2023). "Overexpression of DUXAP9 was frequently observed in moderate/poor pathological grade, advanced clinical stage, lymph node metastasis, worse overall survival (OS), and worse disease‐specific survival (DSS)." (PMID 37401236, 2023).
oral squamous cell carcinoma (1 paper, 2023). "The authors identify a lncRNA DUXAP9 is highly correlated with poor clinicopathological features in oral squamous cell carcinoma (OSCC) patients." (PMID 37401236, 2023).
cancer (5 papers, 2019 to 2023). A tumor composed of atypical neoplastic, often pleomorphic cells that invade other tissues. "It is generally appreciated that the activation of oncogenic transcription factors (TFs) contributes to the aberrant expression of lncRNAs in cancer, and hence, we searched for transcription factors that potentially regulate the upregulation of DUXAP9 in OSCC." (PMID 37401236, 2023). "To verify DUXAP9 expression in cancer, we performed a pancancer analysis that compared tumor tissues and paracancerous tissues using The Cancer Genome Atlas (TCGA) database." (PMID 37401236, 2023). "Two pseudogenes DUXAP8 and DUXAP9 were significantly upregulated in cancer samples compared with normal samples." (PMID 31409759, 2019). "Expression of DUXAP8, DUXAP9, COL1A1 and COL1A2 were significantly increased in cancer samples compared to normal controls while miR-29c-3p expression was decreased." (PMID 31409759, 2019). "qPCR showed that DUXAP8, DUXAP9, COL1A1 and COL1A2 were significantly upregulated in renal cell carcinoma cancer samples compared with normal controls whereas miR-29c-3p expression in cancer tissues was decreased." (PMID 31409759, 2019).
tumor (5 papers, 2019 to 2023). "The mice injected with DUXAP9‐overexpressing reporter cells form more tumor nodules in their lungs than the mice injected with vector cells." (PMID 37401236, 2023). "The expression of DUXAP9 is also higher in genotype‐tissue expressed (GTEx) OSCC tumor samples from TCGA than in their corresponding paracancerous controls." (PMID 37401236, 2023). "The knockdown of DUXAP9 significantly reduced tumor volumes and weights in the knockdown group compared with the control group." (PMID 37401236, 2023). "The results showed a consistent tendency for DUXAP9 expression to be increased in ccRCC tissues compared to adjacent non-tumor tissues (P<0.001)." (PMID 34168980, 2021). "We first examined DUXAP9 expression in 112 pairs of primary localized ccRCC and adjacent non-tumor tissues from SYSUCC Biobank." (PMID 34168980, 2021). "And DUXAP9 involved with activity of PI3K/Akt/GSK3β/Snail pathway in ccRCC tumor tissues need further verification." (PMID 34168980, 2021). "In this study, we characterized a lncRNA DUXAP9 and the upregulation of DUXAP9 was analyzed by quantitative real-time PCR in 112 pairs of localized ccRCC tumor tissues compared with adjacent normal tissues." (PMID 34168980, 2021). "In the present study, our results made a more particular knowledge of that lncRNA DUXAP9 is an extremely important factor in promoting the tumor progression of localized ccRCC." (PMID 34168980, 2021). "Using an experimental mouse xenograft model, we found that DUXAP9‐206‐transduced cells showed faster tumour growth rates than vector‐control cells." (PMID 30515972, 2019). "In situ hybridization (ISH) analysis using a specific probe revealed that the expression levels of DUXAP9‐206 were significantly elevated in NSCLC tumour tissues compared with paired adjacent non‐tumour tissues." (PMID 30515972, 2019). "The RNAscope assay also showed that DUXAP9 is enriched in OSCC tumor tissues." (PMID 37401236, 2023). "They concluded that Lnc-DUXAP9 might promote tumour proliferation via IGF2BP2/Lnc-DUXAP9/PI3K/Akt axis." (PMID 37284313, 2023). "To test DUXAP9 expression in the regulation of tumorigenesis in vivo, we subcutaneously injected DUXAP9 knockdown OSCC cells into null mice and monitored tumor formation for 3 weeks." (PMID 37401236, 2023). "We explored whether DUXAP9 is involved in Akt-induced EMT, tumor growth, and invasiveness." (PMID 34168980, 2021).
DUXAP9 also shares sentences with these, for which no sentence is quoted: bladder cancer (2 papers); Oral leukoplakia (1); thyroid cancer (1).